OR2AE1 (olfactory receptor family 2 subfamily AE member 1)
Description:
Odorant receptor.
Synonyms: OR2AE2
Tractability: Antibody: UniProt places it where antibodies can reach, with medium confidence; UniProt predicts a signal peptide or a membrane-spanning region; its Gene Ontology location is reachable by antibodies, with medium confidence.
Gene: Protein-coding gene on chromosome 7 (99,876,062 to 99,877,033, reverse strand). Ensembl gene ENSG00000244623.
Subcellular location: Cell membrane
Pathways (Reactome):
Sensory Perception: Expression and translocation of olfactory receptors
Gene Ontology:
Molecular function: olfactory receptor activity; G protein-coupled receptor activity
Biological process: detection of chemical stimulus involved in sensory perception of smell; G protein-coupled receptor signaling pathway
Cellular component: plasma membrane; membrane
Genetic constraint (gnomAD): Loss-of-function variants: 2 observed, 1.66 expected, observed/expected ratio (o/e) 1.2, 90% interval 0.41 to 1.9. That is too few expected variants to judge how well the gene tolerates losing a copy. Missense variants: 400 observed, 417.38 expected, observed/expected ratio (o/e) 0.96, 90% interval 0.88 to 1.04. Synonymous variants: 159 observed, 163.29 expected, observed/expected ratio (o/e) 0.97, 90% interval 0.86 to 1.11.
Homologues: Orthologues: chimpanzee OR2AE1 (98% identical), macaque OR2AE1 (92% identical), dog OR2AE1 (84% identical). Paralogues in human: OR2M2 (50% identical), OR2M4 (49% identical), OR2AJ1 (49% identical), OR2M5 (49% identical), OR2M7 (49% identical), OR2T1 (48% identical), OR2V2 (48% identical), OR2M3 (47% identical), OR2T27 (47% identical), OR2T29 (47% identical), OR2T5 (47% identical), OR2V1 (47% identical), and 80 more.
Diseases named in the same sentence as OR2AE1 in open-access papers:
OR2AE1 is named in the same sentence as 2 diseases in open-access papers, as found by Europe PMC text mining. Sharing a sentence is not in itself a finding about the gene and the disease.
OR2AE1 shares sentences with these, for which no sentence is quoted: cancer (1 paper); gastric cancer (1).